PRDM16 (PR/SET domain 16)
Diseases named in the same sentence as PRDM16 in open-access papers (continued):
Sharing a sentence is not in itself a finding about the gene and the disease.
Hyperglycemia (5 papers, 2016 to 2026). An increased concentration of glucose in the blood. "If we hypothesize that these lower DNA methylation levels at PRDM16 were programmed in utero and were already decreased at birth, our results are concordant since the adverse environment created by maternal hyperglycemia was associated with lower DNA methylation levels at the PRDM16 gene locus." (PMID 27340502, 2016). "In the current study, we tested in two independent birth cohorts whether the fetal exposure to maternal hyperglycemia is associated with placental DNA methylation variations in genes involved in BAT/wBAT genesis, specifically targeting the PRDM16, BMP7, CTBP2, and PPARGC1α gene loci." (PMID 27340502, 2016). "In brief, the current results with PRDM16 and BMP7 suggest that brown/beige adipogenesis is increased in response to an exposure to maternal hyperglycemia." (PMID 27340502, 2016).
Sepsis (5 papers, 2021 to 2025). Sepsis is defined as life-threatening organ dysfunction caused by a dysregulated host response to infection. "Accumulating evidence suggests a strong association between sepsis and fatty acid oxidation, with PRDM16 emerging as a pivotal regulator of fatty acid oxidation." (PMID 39549609, 2024). "The collective evidence suggests a potential association between PRDM16 and sepsis." (PMID 39549609, 2024). "Third, while the role of the PRDM16/NRF2/GPX4 axis in sepsis-related injury has been well studied, more research is needed to understand its role in COPD, asthma, and PAH." (PMID 41199815, 2025). "In summary, PRDM16 overexpression mitigates sepsis-induced multi-organ injury via upregulation of the NRF2/GPX4 axis." (PMID 39549609, 2024). "The current research presents novel findings indicating that PRDM16 suppressed ferroptosis to ameliorate sepsis-induced multiple organ injury, including AKI." (PMID 39549609, 2024). "In sepsis models, poly (lactide-co-glycolic acid)-encapsulated FMN (PLGA-FMN) significantly upregulates PRDM16 expression and activates the NRF2/GPX4 pathway, effectively inhibiting ferroptosis and reducing sepsis-associated multiorgan injury, including lung damage." (PMID 41199815, 2025). "In addition, CLP-induced sepsis also attenuated catabolic pathways, reducing expression of Prdm16 and lipolysis-related genes." (PMID 34322037, 2021). "PRDM16 plays a role in inhibiting ferroptosis through the NRF2/GPX4 axis or GPX4, thereby helping to prevent multi-organ injury induced by sepsis, which includes acute kidney injury (AKI)." (PMID 40867920, 2025). "In septic foals, several genes, including PRDM16, WRAP53, LTF, and VLDLR, were activated to address inflammation or enhance survival rates in sepsis." (PMID 40867920, 2025). "In the present research, several genes linked to ER stress-response genes were identified, including PRDM16, WRAP53, LTF, and VLDLR, which exhibited increased expression in sepsis." (PMID 40867920, 2025). "Collectively, these findings reveal that PRDM16 is a novel suppressor of ferroptosis and that targeting PRDM16 using PLGA-encapsulated formononetin represents a new therapeutic strategy for sepsis-induced multiple organ injury, including AKI." (PMID 39549609, 2024). "In our research, it was demonstrated for the first time that PLGA-encapsulated formononetin upregulates PRDM16, which activates the NRF2/GPX4 pathway, thereby inhibiting ferroptosis and reducing sepsis-induced multi-organ injury, including AKI." (PMID 39549609, 2024). "The current investigation indicates that PRDM16 expression is elevated in mouse kidneys, BUMPT, and HK-2 cells following sepsis injury." (PMID 39549609, 2024). "Overall, our findings demonstrated that PRDM16 suppresses ferroptosis via the NRF2/GPX4 axis or directly through GPX4, as confirmed by PT-PRDM16-KO, PT-PRDM16-KI, and ADV-PRDM16 plasmid experiments in sepsis mice induced by CLP." (PMID 39549609, 2024).
Cachexia (4 papers, 2022 to 2024). Severe weight loss, wasting of muscle, loss of appetite, and general debility related to a chronic disease. "Furthermore, in addition to human studies, the upregulation of markers indicative of BAT, such as PR domain zinc finger protein 16 (PRDM16) and uncoupling protein 1 (UCP1), could also be elucidated in the C26-induced cachexia murine model." (PMID 38791998, 2024).
Hypertension (4 papers, 2023 to 2025). The presence of chronic increased pressure in the systemic arterial system. "Notably, GWAS and PheWAS have shown that the PRDM16 gene–associated single nucleotide polymorphisms are significantly associated with BP-related traits, including DBP, SBP, hypertension, CAD, and any stroke." (PMID 39625782, 2024).
myeloid leukemia (4 papers, 2008 to 2020). A clonal proliferation of myeloid cells and their precursors in the bone marrow, peripheral blood, and spleen. "Additionally, retroviral integrations in Prdm16 in mouse hematopoietic cells has been associated with myeloid leukemia, as well as the immortalization of progenitor cells." (PMID 19043588, 2008). "PRDM16 is a 140 kDa zinc-finger protein containing PR-(PRD1-BF-1-RIZ1 homologous) domain that was originally identified at a chromosomal breakpoint in human myeloid leukemia cells." (PMID 23166672, 2012).
astrocytoma (3 papers, 2016 to 2026). "Our previous report identified PR domain containing 16 (PRDM16), a member of the PR-domain gene family, as a new methylation associated gene in astrocytoma cells." (PMID 26701852, 2016). "Likewise, an association of PRDM16 promoter methylation with expression levels was recently reported in adipose tissue, colorectal cancer and astrocytoma cells." (PMID 41566085, 2026). "In addition to hypomethylation, miRNA dysregulation is also one of the causes of PRDM16 overexpression in astrocytoma cells." (PMID 26701852, 2016). "For example, miR-101 a tumor suppressor in glioma, was shown to reverse hypomethylation of the PRDM16 promoter in astrocytoma cells and directly inhibit PRDM16 expression." (PMID 41566085, 2026). "The methylation frequency of PRDM16 increased in astrocytoma cells transfected with miR-101 mimics, while miR-101 reversed the DNA hypomethylation levels of the PRDM16 promoter." (PMID 26701852, 2016). "In this study, the ectopic expression of miR-101 induced cellular apoptosis and disrupted the function of mitochondria within astrocytoma cells by direct or epigenetic regulation of PRDM16." (PMID 26701852, 2016). "We used qRT-PCR and western blot techniques to examine the endogenous expression of PRDM16 in the presence of miR-101 in different astrocytoma cell lines." (PMID 26701852, 2016). "The present study confirms that PRDM16 is a hypomethylated gene that can be overexpressed in astrocytoma patients and demonstrates that the hypomethylation status of the PRDM16 promoter can predict poor prognoses for astrocytoma patients." (PMID 26701852, 2016). "The levels of PRDM16 methylation in 50 astrocytoma tissues were lower than those in 10 normal brain tissuesamples." (PMID 26701852, 2016). "In this study, we confirmed that PRDM16 is a new hypomethylated gene in astrocytoma cells and we found that hypomethylation is one of the mechanisms responsible for high PRDM16 expression levels." (PMID 26701852, 2016). "We authenticatedd the oncogenetic role of the hypomethylated gene PRDM16 and its effect on mitochondrial function and cell apoptosis as regulated by miR-101 in astrocytoma cells." (PMID 26701852, 2016). "We investigated the methylation status ofthe PRDM16 promoter in four astrocytoma cell lines using MSP." (PMID 26701852, 2016). "In addition, PRDM16 is hypomethylated and overexpressed in astrocytoma, whereas it is hypermethylated in lung and esophageal cancers." (PMID 29435136, 2018). "PRDM16 expression was amplified in astrocytoma malignant grades." (PMID 26701852, 2016). "PRDM16 protein levels were amplified in astrocytoma cell lines and in 39 of 50 astrocytoma tissues." (PMID 26701852, 2016). "Therefore PRDM16 can be considered a potential marker for the prognosis of astrocytoma patients." (PMID 26701852, 2016). "Thus, PRDM16 may be considered a new target of miR-101 in astrocytoma cell lines." (PMID 26701852, 2016). "PRDM16, LMO3 and CPEB1 are hypomethylated genes in astrocytoma cells and because CPEB1 and LMO3 have been confirmed as epigenetic targets of miR-101, we examined the effects of miR-101 on the methylation status of PRDM16 by BSP." (PMID 26701852, 2016). "Although the hypomethylation frequencies of PRDM16 in higher-grade astrocytomas (WHO grades III and IV) were higher than those in lower-grade astrocytomas (WHO grades I and II), no statistical correlation was found between PRDM16 expression and sex, age or histological grade." (PMID 26701852, 2016).
diabetic kidney disease (3 papers, 2024 to 2025). Progressive kidney disorder caused by vascular damage to the glomerular capillaries, in patients with diabetes mellitus. "Recent findings from our research indicated that the PRD1-BF1-RIZ1 homeodomain protein 16 (PRDM16) inhibited the progression of diabetic kidney disease (DKD)." (PMID 39549609, 2024).
endothelial dysfunction (3 papers, 2025 to 2026). In vascular diseases, endothelial dysfunction is a systemic pathological state of the endothelium (the inner lining of blood vessels) and can be broadly defined as an imbalance between vasodilating and vasoconstricting substances produced by (or acting on) the endothelium. "Endothelial cell–specific Prdm16 knockout (EC-Prdm16 KO) mice exhibit impaired arterial blood flow recovery due to endothelial dysfunction." (PMID 41528566, 2026).
esophageal cancer (3 papers, 2017 to 2020). A primary or metastatic malignant neoplasm involving the esophagus. "Similarly, PRDM16 hypomethylation was also described in glioblastoma whereas a study suggested that PRDM16 hypermethylation level might be used as a potential biomarker for the diagnosis of esophageal cancer." (PMID 32290321, 2020). "The methylation levels of APC, ITGAV, PRDM16 and PTX3 were significantly different between esophageal cancer and healthy control tissues." (PMID 27893424, 2017).
Maturity onset diabetes (3 papers, 2016 to 2025). "Pathway analysis for CACNA1A and PRDM16, the two genes suggestively associated with tea consumption, showed enrichment for white Adipose tissue browning (P = 3.2 × 10−5), nNOS signalling in skeletal muscle cells (P = 3.6 × 10−3) and Maturity onset diabetes of young (MODY) (P = 5.2 × 10−3)." (PMID 33990564, 2021).
metabolic syndrome (3 papers, 2014 to 2025). A cluster of metabolic risk factors for CARDIOVASCULAR DISEASES and TYPE 2 DIABETES MELLITUS. "These association tests have shown that SNPs within the PRDM16 gene were associated with metabolic syndrome phenotypes." (PMID 24863034, 2014).
renal fibrosis (3 papers, 2024 to 2025). A final common manifestation of a wide variety of chronic kidney diseases characterized by glomerulosclerosis and tubulointerstitial fibrosis. "We further demonstrated that tubular-specific knockout of PRDM16 aggravated the progression of renal fibrosis." (PMID 40758676, 2025). "Tubular-specific knockout of Prdm16 promoted renal fibrosis in models of unilateral ureteral occlusion (UUO) and unilateral ischemia-reperfusion injury (UIRI) by exacerbating mitochondrial dysfunction." (PMID 40758676, 2025). "We also demonstrated that renal fibrosis was attenuated by PRDM16 overexpression, as the mRNA levels of Col1a1, Col3a, Fibronectin, and Vimentin, the protein levels of Fibronectin and α-SMA, and collagen deposition decreased." (PMID 40758676, 2025). "The tubular-specific knockout of PRDM16 aggravated renal fibrosis and mitochondrial dysfunction in unilateral ureteral occlusion (UUO) and unilateral ischemia-reperfusion injury (UIRI) mice." (PMID 40758676, 2025). "We report PRDM16 as a potential downstream target of TGF-β signaling that attenuates renal fibrosis by safeguarding tubular mitochondrial function." (PMID 40758676, 2025). "Delivery of the exogenous PRDM16 gene preserved renal function and ameliorated the progression of renal fibrosis by protecting mitochondrial function." (PMID 40758676, 2025). "Delivery of the exogenous PRDM16 gene attenuated renal fibrosis and preserved tubular mitochondrial function by upregulating PGC-1α." (PMID 40758676, 2025). "In our previous study, NF-κB was found to mediate the upregulation of PRDM16, thereby inhibiting renal fibrosis through the transient receptor potential ankyrin 1 (TRPA1)/mitogen-activated protein kinase (MAPK)/transforming growth factor-β1 (TGF-β1) axis." (PMID 39549609, 2024). "Our previous study reported that formononetin directly binds to and upregulates PRDM16 expression, subsequently inhibiting renal fibrosis in diabetic mice." (PMID 39549609, 2024). "In this study, we show that NF‐ κ B mediates the upregulation of PRDM16, which suppresses renal fibrosis in early DKD." (PMID 38072665, 2024). "In summary, this study identified a potential target, PRDM16, for attenuating renal fibrosis." (PMID 40758676, 2025). "PRDM16 attenuated the progression of renal fibrosis by protecting tubular mitochondrial function." (PMID 40758676, 2025). "Furthermore, a folic acid–induced renal fibrosis model was established to verify the renoprotective role of PRDM16." (PMID 40758676, 2025). "Whether PRDM16 plays a hostile role in renal fibrosis needs further study." (PMID 40758676, 2025). "We further determined whether TRPA1 acts downstream of PRDM16 for suppressing renal fibrosis." (PMID 38072665, 2024). "PRDM16 protects kidney function by counteracting TGF-β-induced mitochondrial damage, offering a potential therapeutic target for preventing renal fibrosis in chronic kidney disease." (PMID 40758676, 2025). "Whether PRDM16 expressed by perirenal adipocytes plays an important role in PRAT browning, other metabolic changes, and renal fibrosis remains to be further studied." (PMID 40758676, 2025).
abdominal aortic aneurysm (2 papers, 2023 to 2024). Enlargement and ballooning of the vessel that supplies arterial blood to the abdomen, pelvis and legs. "Importantly, PRDM16 is most highly expressed in the aorta and artery, and single-cell RNA-Seq (scRNA-Seq) analysis in aortas from both humans and mice revealed that PRDM16 is predominantly expressed in VSMCs, where it protects against abdominal aortic aneurysm." (PMID 39625782, 2024).
acute kidney injury (2 papers, 2025). Sudden and sustained deterioration of the kidney function characterized by decreased glomerular filtration rate, increased serum creatinine or oliguria. "Recent studies demonstrated that PRDM16 suppresses ferroptosis to protect against acute kidney injury through the NRF2-GPX4 axis." (PMID 41197355, 2025).
aneurysm (2 papers, 2024 to 2025). Bulging or ballooning in an area of an artery secondary to arterial wall weakening. "Notably, a recent study found that Prdm16 ablation aggravates elastase-induced aneurysms in mice, through upregulation of ADAM12 and inflammatory signaling." (PMID 41107595, 2025).
breast tumors (2 papers, 2014 to 2023). "In our research, expression of marker genes of fat browning, like UCP1, PRDM16, CIDEA, COX7A1, PGC1α, TMEM26 and TBX1, was up-regulated in adipose tissue adjacent to breast tumors." (PMID 25291184, 2014).
cleft palate (2 papers, 2010 to 2024). Cleft palate is a fissure type embryopathy that affects the soft and hard palate to varying degrees. "Global mutations in PRDM16 are associated with cleft palate, altered craniofacial development, and impaired cardiac development." (PMID 39351529, 2024).
dilated cardiomyopathy (2 papers, 2024). "PRDM16 has been shown to play an important role in cardiomyocytes, and the loss of PRDM16 causes dilated cardiomyopathy and left ventricular noncompaction cardiomyopathy." (PMID 39408732, 2024). "Extensive research has linked Prdm16 to left ventricular non-compaction (LVNC) and dilated cardiomyopathy (DCM)." (PMID 38542214, 2024).
Headache (2 papers, 2017 to 2023). Cephalgia, or pain sensed in various parts of the head, not confined to the area of distribution of any nerve. "The gene-based association study identified 51 genes (cut-off p value = 0.05/19,436 = 2.57 × 10–6) that were associated with headaches, with the PR/SET domain 16 (PRDM16) gene showing the strongest association (p value of 7.10 × 10–15)." (PMID 36939796, 2023).
Hydrocephalus (2 papers, 2021 to 2025). Hydrocephalus is an active distension of the ventricular system of the brain resulting from inadequate passage of CSF from its point of production within the cerebral ventricles to its point of absorption into the systemic circulation. "According to the function of PRDM16 in normal development, loss of Prdm16 might contribute to several problems including the craniofacial and cardiac defects and hydrocephalus of the syndrome." (PMID 33597191, 2021). "In addition, we found that Prdm16 cKO mice often exhibit hydrocephalus, a phenotype commonly observed in mice with ependymal cell defects." (PMID 40683857, 2025).
hypogonadism (2 papers, 2024 to 2025). A disorder characterized by decreased function of the gonads. "Our study supports that molecular shift from the adipogenic to the myogenic pathway in men with hypogonadism treated with T could be mediated directly or indirectly by enhanced PRDM16 activity, in turn a result from increased estradiol level." (PMID 39286266, 2024).
lung squamous cell carcinomas (2 papers, 2019 to 2022). "In addition, downregulation of MECOM and PRDM16 expression was also found in LUAD and lung squamous cell carcinomas (LUSC) in the TIMER database (all p < 0.05)." (PMID 35174083, 2022).
lymph node metastasis (2 papers, 2022 to 2024). "The IHC results also showed that the expression of the IGSF9, PRDM16, and ALDH2 proteins was significantly associated with a higher level of lymph node metastasis." (PMID 35013309, 2022). "Reduced copy numbers of IGSF9 and PRDM16 and the increased copy number of ALDH2 were intricately intertwined with lymph node metastasis and reduced survival rates in IMPC patients." (PMID 38181281, 2024). "The correlation analyses showed that IGSF9 and PRDM16 protein levels inversely correlated with lymph node metastasis (IGSF9, R = −0.32, P < 0.01; PRDM16, R = −0.336, P < 0.01), while ALDH2 protein expression positively correlated with lymph node metastasis (ALDH2, R = 0.262, P < 0.05)." (PMID 35013309, 2022).
pancreatic cancer (2 papers, 2020 to 2023). "Thus, inactivation of Prdm16 throughout embryonic development and postnatal life was insufficient to perturb pancreas homeostasis or drive sporadic pancreatic cancers." (PMID 36828547, 2023).